SOX2 (SRY-box transcription factor 2)
Diseases named in the same sentence as SOX2 in open-access papers (continued):
Sharing a sentence is not in itself a finding about the gene and the disease.
lung adenocarcinoma (57 papers, 2010 to 2025). A carcinoma that arises from the lung and is characterized by the presence of malignant glandular epithelial cells. "The lncRNA MALAT1 (Metastasis-Associated Lung Adenocarcinoma Transcript 1) also appears to influence the expression of SOX2." (PMID 28388544, 2017). "Evidence indicates that CAMK2A promotes tumor-initiating capacity in lung adenocarcinoma by enhancing SOX2 expression through EZH2 phosphorylation, highlighting its complex involvement in tumor biology." (PMID 41180485, 2025). "SOX2 acts as a transcription factor in cells and serves as an independent prognostic indicator of poor outcome in lung adenocarcinoma." (PMID 37081975, 2023). "This novel distal cluster contains two regions located 124 and 134 kb downstream of the SOX2 promoter that drive transcription in breast and lung adenocarcinoma cells." (PMID 37738673, 2023). "Using gain-of-function and loss-of-function genetic models, we discovered that active Notch signaling and low Sox2 levels dictate the ability of type II cells to proliferate and progress into lung adenocarcinoma upon KrasG12D activation." (PMID 37882674, 2023). "It is more surprising, however, that the SOX2 gene is regulated by common enhancers in both breast and lung adenocarcinoma cells as enhancers are usually highly tissue specific." (PMID 37738673, 2023). "We propose that aberrant up-regulation of the pioneer factor FOXA1 recommissions both SRR124 and SRR134 in tumor cells, driving SOX2 overexpression in breast and lung adenocarcinoma." (PMID 37738673, 2023). "We found that, in breast and lung adenocarcinoma, SOX2 is driven by a novel developmental enhancer cluster we termed SRR124–134, rather than the previously identified SRR1, SRR2 or the SCR." (PMID 37738673, 2023). "We have previously demonstrated that the proximal respiratory epithelial lineage marker Sox2 inhibits Kras-induced lung adenocarcinoma formation potentially due to its inhibitory effect on Notch signaling." (PMID 37882674, 2023). "The genomic amplification of Sox2 was detected in about 20% of lung adenocarcinoma patients and its high expression was significantly associated with a lower overall survival." (PMID 34771484, 2021). "SOX2 amplification and overexpression have also been reported as independent poor prognostic predictors of stage I lung adenocarcinoma." (PMID 32098209, 2020). "Embryonic stem cell transcription factors like Oct4, Sox2 and Nanog contribute to the genesis and maintenance of the CSCs14,15 and Sox2 is especially important for the self-renewal of stem-like cells from lung adenocarcinomas." (PMID 32170113, 2020). "Our lab had reported that the embryonic stem cell transcription factor Sox2 is indispensable for the self-renewal of SP cells from lung adenocarcinomas, while Oct4 and Nanog had a relatively lesser role." (PMID 30322398, 2018). "It is of interest to note that the SOX2 gene is much more frequently amplified in LSQCC (72%) than in lung adenocarcinomas (8%)." (PMID 30060526, 2018). "Our earlier studies had demonstrated that Sox2 was necessary for the self-renewal of SP cells from lung adenocarcinoma cell lines." (PMID 30322398, 2018). "It has been shown that miR-145 expression is negatively correlated with the levels of Oct4/Sox2/Fascin1 in lung adenocarcinoma and an Oct4(high)/Sox2(high)/Fascin1(high)/miR145(low) phenotype, as in the present study, predicted poor prognosis." (PMID 29348831, 2017). "On contrary, SOX2 expression is suggested a poor prognosis predictor in stage I lung adenocarcinoma." (PMID 26780934, 2016). "KRT6A is a member of the cytokeratin gene family, and recently it was reported that ectopic SOX2 over-expression up-regulated the KRT6A mRNA level in a lung adenocarcinoma cell line." (PMID 21304604, 2011).
lung adenocarcinoma (continued). "We next attempted to analyze SOX2 expression at the protein level in histological tissue specimens representing different stages in the pathogenesis of lung adenocarcinomas and SCCs." (PMID 20161759, 2010). "Moreover, the USP13-mediated deubiquitination process directly upregulated MYC protein levels with increased expression of SOX2 and squamous features in KP mouse and human lung adenocarcinoma cells." (PMID 38093367, 2023). "Since Sox2 plays a significant role in the maintenance and survival of CSCs from lung adenocarcinoma cells, we carried out the ChIP assays in stem-like side population (SP) cells isolated from H1650 lung adenocarcinoma cells." (PMID 32170113, 2020). "We first sought to elucidate whether nicotine enhances self-renewal through induction of Sox2 in A549 and H1650 lung adenocarcinoma cell lines, and whether e-cigarette extracts had similar effects compared to nicotine." (PMID 30322398, 2018). "We transduced OCT3/4, SOX2, and KLF4 (hereafter, OSK) or EGFP into a KRAS-mutated (G12S) human lung adenocarcinoma cell line (A549) using retrovirus vectors, then cultured the cells in 10% fetal bovine serum (FBS) containing Dulbecco’s modified Eagle’s medium (DMEM)." (PMID 28951614, 2017). "Knockdown of SOX2 using siRNAs abrogated the tumor initiation of lung adenocarcinoma CSCs/CICs." (PMID 26751205, 2016). "There may be mechanisms other than SOX2 gene amplification driving increased SOX2 protein, particularly in lung adenocarcinomas." (PMID 23620753, 2013). "Since SOX2 mRNA levels were largely higher in SCCs than adenocarcinomas of the lung, we questioned whether a SOX2-related signature can discriminate between the two subtypes of NSCLC." (PMID 20161759, 2010). "In addition, we found marked SOX2 protein expression only in the pathogenesis of SCC which was greatly higher in SCCs relative to lung adenocarcinomas following analyses of two independent and large tissue microarray (TMA) sets." (PMID 20161759, 2010). "Moreover, a previously characterized OCT4/SOX2/NANOG embryonic stem cell expression signature effectively separated SCCs from lung adenocarcinomas when analyzed in publicly available NSCLC microarray datasets." (PMID 20161759, 2010). "Also, the direct association of stem-like cells with generation of metastatic disease may be supported by our observation where a significant correlation was observed between high Sox2 expressions in the metastatic tumors of lung adenocarcinoma patients." (PMID 23009336, 2012). "METTL3 enhances translation of oncogene BRD4 through forming an mRNA loop in lung adenocarcinoma, and promotes expression of SRY (sex-determining region Y)-box 2 (SOX2) through IGF2BP2-directed suppression of RNA degradation in CRC." (PMID 36936424, 2023). "In lung adenocarcinoma, an effector of Hippo pathway, YAP, plays a crucial role in the maintenance of stemness by physical interaction with Sox2 and Oct4." (PMID 36514170, 2022). "Immunohistochemical (IHC) staining performed on 12 lung adenocarcinoma (LA) tissue samples showed protein expression of OCT4, NANOG, SOX2, KLF4 and c-MYC, and the CSC marker CD44." (PMID 34685477, 2021). "Examination of the TCGA database show that CDK9 expression is elevated in lung adenocarcinomas and high expression of CDK9, SOX2, and SOX9 correlates with poor overall survival." (PMID 34359807, 2021). "The most significantly focally amplified genes in lung adenocarcinomas are NKX2-1, MYC, TERT, MCL1 and MDM2, while in LSQCC the most amplified were SOX2, CCND1, FGFR1, MYC, YES1, MIR205 and EGFR." (PMID 30060526, 2018). "Although lung adenocarcinoma (ADC) harbor significantly lower amounts of SOX2 as compared to SCC, SOX2 overexpression has mostly been correlated with a poor clinical outcome." (PMID 29596469, 2018).
lung adenocarcinoma (continued). "Recently, Dogan and colleagues investigated SOX2 and EGFR inhibitors in lung adenocarcinoma cell lines." (PMID 25114775, 2014). "In fact, amplification and/or overexpression of SOX2 have been reported in lung SCC, lung adenocarcinoma and, more recently, small-cell lung cancer." (PMID 24736592, 2014). "Besides, lung adenocarcinoma cells with P4HA1 knockdown showed decreasing OCT4, SOX2, NANOG protein levels." (PMID 34659558, 2021). "Furthermore, the continuous activation of EGFR leads to an increase in Sox2 expression, resulting in the maintenance of LCSC features in EGFRm lung adenocarcinoma." (PMID 34771484, 2021). "Particularly, half of lung SCC categorized as FISH+, with true gene amplification occurring in 13.8% of cases, while lung adenocarcinomas presented increased SOX2 gene copy number in 10.7% of samples with no cases harbouring true gene amplification." (PMID 24736592, 2014). "Our findings contrast with those of another study where a negative survival impact for SOX2 low level amplification, compared to lack of amplification, was observed in lung adenocarcinoma." (PMID 24736592, 2014). "Spheres derived from the lung adenocarcinoma cell line, H1299, exhibited a contraction of the S-phase of the cell cycle compared with monolayer cultures, consistent with a non-replicating state, and enrichment of the stemness markers KLF4, Notch-1, Nanog and Sox2." (PMID 29651165, 2018). "Therefore, further targeting SOX2 in EGFR-mutant cancer with PI3K/AKT inhibitors in lung adenocarcinoma cell lines, may yield better results." (PMID 25114775, 2014). "In addition, we found that SOX2 protein was completely absent in lung adenocarcinoma pathogenesis and highly expressed in SCC development." (PMID 20161759, 2010). "Notably, we also analyzed a set of lung adenocarcinomas and found no significant SOX2 copy number gain further demonstrating a cell-lineage expression pattern for SOX2 specifically in lung SCCs." (PMID 20161759, 2010). "In lung adenocarcinomas, expression of SOX2 but not NANOG was detected in approximately 50% of stage I tumors, whereas another study reported NANOG expression without SOX2, hence suggesting a SOX2-independent regulatory mechanism of NANOG expression in these tumors." (PMID 32635524, 2020).
medulloblastoma (55 papers, 2011 to 2026). A malignant, invasive embryonal neoplasm arising from the cerebellum. "Human medulloblastomas with CoREST signatures showed an increase in expression of well-established stemness-associated transcription factor gene-sets (e.g. Nanog, Oct4, Sox2)." (PMID 35379950, 2022). "Quiescent SOX2+ tumor cells seed for medulloblastoma-propagating cells (MPCs) and cause relapse in SHH medulloblastoma." (PMID 30517668, 2020). "Treatment with JQ1 strongly suppressed expression of SOX2, Nestin and Nanog, all genes associated with neural stem cells and medulloblastoma." (PMID 24796395, 2014). "Under these differentiation conditions, control cells completely lost expression of Sox2 with 7 days, while approximately 60% of Ahr-deficient medulloblastoma CPCs retained high levels of Sox2 expression, indicative of a retention of an undifferentiated phenotype." (PMID 31924815, 2020). "Recently SOX2 was also directly implicated in medulloblastoma." (PMID 24796395, 2014). "Thus, our data suggest that ectopically elevating SOX2 in DAOY medulloblastoma cells causes them to undergo physiological changes that resemble a more differentiated phenotype." (PMID 22937156, 2012). "In medulloblastoma—a childhood brain tumour—IGFBP-2 is instrumental for the SOX2-driven Shh subtype." (PMID 40429889, 2025). "A subset of medulloblastomas show high expression of SOX2, suggesting a subpopulation of patients with aggressive disease." (PMID 36932385, 2023). "In a mouse model of sonic hedgehog (SHH) medulloblastoma, high SOX2 expression is present in a small subpopulation of cells that proliferate infrequently." (PMID 35454854, 2022). "SOX2 expression in mouse models of SHH medulloblastoma has been demonstrated to be restricted to a subpopulation consisting of approximately 5% of tumor cells that exist in a slowly cycling state." (PMID 35454854, 2022). "Concordantly, SOX2 expression is higher in SHH-activated medulloblastomas than it is in other medulloblastoma subtypes with SOX2 activity serving as a regulator of stemness in these tumors." (PMID 34012965, 2021). "SOX2 co-immunoprecipitation identified a number of interacting proteins in medulloblastomas cells, including Usp9x and Usp34." (PMID 33613844, 2021). "The role of Sox2 involves both tumorigenesis and tumor maintenance; it is a stem cell driver, and Sox2 is now considered a cancer stem cell marker of medulloblastoma cells." (PMID 33066274, 2020). "Their genetic fate mapping and limiting dilution transplantation assay demonstrated SOX2 as a cancer stem cell marker in medulloblastoma and skin squamous cell carcinoma (SCC)." (PMID 30517668, 2020). "In a mouse model of sonic hedgehog subgroup medulloblastoma, elevated SOX2 expression is observed in a minor, quiescent subpopulation within the tumor that is able to resist chemotherapy and drive tumor recurrence." (PMID 32998722, 2020). "We profiled Tuj1 expression, in addition to the stem markers Nestin, Olig2 and Sox2 across a panel of 46 medulloblastomas." (PMID 31160565, 2019). "In our screen, CD24+ cells were highly positive for the stem/progenitor marker Sox2, whose expression has been shown to label stem-like cells in the murine brain, and has been shown to be required for SHH-associated medulloblastoma formation." (PMID 30657775, 2019). "SOX2+ cells are also responsible for propagating medulloblastoma and targeting them prevented tumor growth." (PMID 31041783, 2019). "For example, in sonic hedgehog-dependent medulloblastoma, there are more Sox2-positive cells in the EGL, followed by more granule cells." (PMID 30867000, 2019). "As we have seen from various reports, targeting the SHH pathway for inhibition using vismodegib led to increased frequency of quiescent Sox2+ medulloblastoma cells in the Ptch+/− mouse models." (PMID 29298329, 2018).
medulloblastoma (continued). "By using the FLAG tag system and MudPIT, the Sox2 interactome comprising about 280 proteins has been identified in medulloblastoma cells to understand the behavior of Sox2 in brain cancer cells." (PMID 27011181, 2016). "Treatment of medulloblastomas in mice with an anti-mitotic drug or sonic hedgehog (SHH) pathway inhibitor resulted in residual tumors that were enriched in SOX2+ cells, indicating that these cells were likely to contribute toward tumor relapse." (PMID 27791206, 2016). "In DAOY medulloblastoma cells, the ectopical elevation of SOX2 reduced cell density and increased the proportion of quiescent cells and gene markers associated with a more differentiated phenotype." (PMID 25340937, 2014). "In cerebellar granule precursors, which are believed to be the cells of origin for medulloblastoma, Shh signaling constitutive activation results in significantly ectopic expression of SOX2." (PMID 24550888, 2014). "JQ1 decreased expression of SOX2 protein in medulloblastoma cells grown under serum free neurosphere promoting culture conditions." (PMID 24796395, 2014). "To identify novel proteins essential for the fate of brain tumor cells, we examined the protein interaction network of the transcription factor, SOX2, in medulloblastoma cells." (PMID 23667531, 2013). "To address this possibility, we used i-SOX2-DAOY cells to examine the long-term effects of SOX2 elevation on the growth of DAOY medulloblastoma cells." (PMID 22937156, 2012). "We already described medullo-spheres from DAOY and ONS-76 cells as a model to study CSC in vitro for evaluating progression and malignancy of medulloblastomas and demonstrated higher expression of β-catenin and Sox-2 in medullo-spheres compared to MB adherent cells." (PMID 34638386, 2021). "Rare quiescent sox2(+) stem cells were identified in a model of medulloblastoma." (PMID 34571996, 2021). "In addition, SOX2 interacts with deubiquitinases Usp34 and Usp9x which can lead to SOX2 stabilization in medulloblastoma cells and was also shown in embryonic stem cells." (PMID 33613844, 2021). "Likewise, mithramycin was able to abrogate tumor growth in medulloblastoma by targeting SOX2-expressing CSCs." (PMID 32295077, 2020). "Similarly, in a mouse model of SHH group medulloblastoma, SOX2 expression within the tumor was found to be restricted to a small quiescent subpopulation." (PMID 32998722, 2020). "CD24 alone could not isolate putative stem cells, but may label cells transitioning from a Sox2 fate to a neural progenitor or radial glial cell fate, cell types frequently observed within medulloblastoma." (PMID 30657775, 2019). "Prior studies analyzed Sox2-eGFP expression in radiation-induced medulloblastomas that form in Ptch+/−/Sox2-eGFP mice to identify stem-like cells, whose properties included self-renewal, tumor recapitulation on transplantation, and the ability to give rise to progeny with diverse differentiation." (PMID 31863004, 2019). "Similarly, elevating SOX2 in medulloblastoma cells, which causes a major reduction in their growth, leads to over a 10-fold increase in the number CD133+ cells just one day after elevating SOX2." (PMID 28388544, 2017). "Likewise, a 3-fold increase in SOX2 levels dramatically reduces DAOY medulloblastoma cell proliferation by ∼90%." (PMID 22937156, 2012). "Furthermore, an interesting phenomenon had been noticed that, in all four subgroups of medulloblastoma, a small group of Wnt-active cells existed and could impair the stemness of CSCs by reducing Bmi-1 and SOX2 levels." (PMID 37370764, 2023). "Ectopic Wnt activation in primary patient-derived medulloblastoma lines proved that the activation of the Wnt/β-catenin pathway in WNT3A-conditioned medium significantly reduced the self-renewal capacity along with the Sox2 and Bmi1 expression in Group 3 and Group 4 medulloblastoma lines." (PMID 34577571, 2021).